EPCAM (epithelial cell adhesion molecule)
Diseases named in the same sentence as EPCAM in open-access papers (continued):
Sharing a sentence is not in itself a finding about the gene and the disease.
lung carcinoma (continued). "Multivariate analysis indicated that local advancement (p = 0.03), MTA1 overexpression (p = 0.001) and EpCAM overexpression (p = 0.045) of the lung cancer tissues remained significant in predicting unfavorable overall survival." (PMID 26698569, 2015). "What’s more, both MTA1 and EpCAM, correlated to each other, were overexpressed in lung cancer tissues and significantly correlated with their clinical stages, tumor diameters, lymph node metastasis." (PMID 26698569, 2015). "We first confirmed the presence of CD133+EpCAM+ cells in freshly obtained tumor tissue and then sought to identify cells of this phenotype in the peripheral blood of patients with lung cancer." (PMID 23959111, 2014). "The CD133 antigen is commonly used to identify normal and CSCs, and anti-EpCAM staining was performed in this study because this molecule is often overexpressed in lung cancers, although its functional role in forming metastases remains controversial." (PMID 23959111, 2014). "To identify these cells, we chose to stain for the CD133 and EpCAM molecules, as these double-positive cells were previously shown to possess stem cell characteristics in lung cancer." (PMID 23959111, 2014). "Then, this technique was further used to investigate the expression of CD133 and EpCAM in the peripheral blood of 41 patients with primary lung cancer." (PMID 23959111, 2014). "EpCAM, a type I transmembrane glycoprotein of ∼40 kDa, is overexpressed in a variety of epithelial tumors, including lung cancer." (PMID 24787949, 2014). "In this study, we examined the association of lung cancer risk in a Chinese population with polymorphisms of the well-established CSC marker genes CD133, ALDH1, Musashi-1 and EpCAM." (PMID 24787949, 2014). "In conclusion, this study confirmed the existence of CD133+EpCAM+ cells in lung tumor tissues and, for the first time, identified these cells in the peripheral blood of patients with lung cancer." (PMID 23959111, 2014). "Primitive progenitor cells expressing CD133 and EpCAM proteins are rare, but they expand in lung cancer compared to the healthy lung." (PMID 23959111, 2014). "EpCAM-targeted molecular therapies are being intensely pursued for several cancers including breast, ovarian, gastric and lung cancer." (PMID 25265904, 2014). "The silencing of G9a expression inhibits the migration and invasion potential of lung cancer cells by enhancing the transactivation of expression of the cell adhesion molecule, epithelial cell adhesion molecule." (PMID 24932239, 2014). "Lung cancer risk was analyzed in a logistic regression model in association with genotypes of four lung CSC marker genes (CD133, ALDH1, Musashi-1, and EpCAM)." (PMID 24787949, 2014). "Spike-in experiments comprising a series of lung cancer cell lines with varying epithelial cell adhesion molecule (EpCAM) expression levels were conducted to assess the capture and purification efficiency of the platform." (PMID 24886394, 2014). "We analyzed the expression of CD24 and CD38 as two potent biomarkers of lung cancer stem cells and EpCAM and ALDH that are used as biomarkers of a wide range of cancer stem cells." (PMID 22592563, 2013). "EpCAM expression was analyzed in both H460 lung carcinoma and A549 human lung adenocarcinoma epithelial derived lungospheres." (PMID 22592563, 2013). "From our previous identification of ZEB1-correlated genes in lung cancer using Affymetrix arrays, we had confirmed regulatory relationships for ST14, EpCAM, and ESRP1 upon ZEB1 gain- and loss-of-function." (PMID 24216980, 2013). "In the human lung carcinoma cell line A549, anti-EpCAM antibody induced a slight (at 10 μM up to 114% as compared with untreated control), but not significant, increase (data not shown)." (PMID 19002182, 2008). "EpCAM may be useful for the surgical oncologist for intraoperative detection of positive LNs from epithelial cancers, including lung cancer, and this warrants further investigation with in vivo studies." (PMID 41087662, 2025).
lung carcinoma (continued). "Markers that enable the effective detection of lung cancer cells in mediastinal LNs include cytokeratin, which is responsible for the structural integrity of epithelial cells, and EpCAM, a membrane glycoprotein that mediates cell–cell adhesion in the epithelium." (PMID 39941799, 2025). "We then hypothesized that EpCAM expression may only correlate with histological subtypes of lung cancer." (PMID 41087662, 2025). "EpCAM may be useful for the surgical oncologist for intraoperative molecular imaging of positive LNs from lung cancer." (PMID 41087662, 2025). "The lung cancer cell-derived exosomes can also induce M2 macrophage polarization, and regulate CD45+EpCAM+ cells apoptosis in lung cancer, and carry circUSP7, which can regulate the miR-934/SHP2 axis in small cell lung cancer (NSCLC) to induce CD8+ T cell dysfunction and anti-PD-1 resistance." (PMID 38633106, 2024). "According to our recent preclinical data, EpCAM-directed CAR T-cell may indeed constitute an effective therapeutic avenue for brain metastases from lung cancer." (PMID 39358663, 2024). "Additionally, certain proteins found on exosome membranes, such as EGFR, placental alkaline phosphatase, EpCam, and Alix, have shown promise as potential prognostic indicators for lung cancer." (PMID 39459055, 2024). "Furthermore, the surface proteins of exosomal membranes, such as EGFR, placental alkaline phosphatase, epithelial cell adhesion molecule (EpCAM), and Alix, serve as noteworthy indicators of long-term survival in patients with lung cancer." (PMID 39459055, 2024). "Furthermore, epithelial gene cadherin 1 (Cdh1) and epithelial cell adhesion molecule (EpCAM) are key features of the epithelial–mesenchymal transition (EMT) process that are significantly hypermethylated in lung cancer." (PMID 37038181, 2023). "Several independent research teams have successively confirmed that the ZEB1‐driven EMT process in lung cancer cells was accompanied by a decrease in the expression of the epithelial cell adhesion molecule E‐cadherin and EPCAM and an increase in the expression of the cytoskeletal protein vimentin." (PMID 36808651, 2023). "Given the differential expression pattern of EpCAM in primary and metastatic lung tumors, the function of EpCAM in different lung cancer stages may also be different." (PMID 36077658, 2022). "Cell surface proteins are used as CSC markers for different types of tumors, for example, cluster of differentiation 34-positive (CD34+)/CD38 − for leukemia cells, CD13/CD45/CD90 for liver cancer, CD117/CD90/epithelial cell adhesion molecule for lung cancer, and CD44 for colon and gastric cancers." (PMID 35148781, 2022). "In clinical practice, the application of the changes in CD45+EpCAM+ cell ratio of PBMCs combined with the changes in CEA and CYFRA21-1serum level and other diagnostic methods may be useful for an early diagnosis of lung cancer." (PMID 36147748, 2022). "In addition, enhanced protein expression of EpCAM was confirmed in murine primary lung tumors in comparison with normal lung tissues by FACS and immunoblotting assays These data together indicated that EpCAM is upregulated in primary lung cancer." (PMID 36077658, 2022). "Taken together, these findings demonstrated that multiple mechanisms including genetic, epigenetic, and tumor microenvironment modulated the dynamic expression patterns of EpCAM in primary and metastatic lung tumors, shedding light on cell isolation, diagnosis, and treatment in lung cancer." (PMID 36077658, 2022). "Therefore, using the area under the ROC curve (ROC/AUC) analysis, the sensitivity, specificity, and accuracy of CEA, ProGRP, NSE, CYFRA21-1, and the ratio of CD45+EpCAM+ cells in PBMCs for the diagnosis of lung cancer were analyzed." (PMID 36147748, 2022).
lung carcinoma (continued). "In summary, our results suggest the increase of CD45+EpCAM+ cell ratio in PBMCs may be useful for early stage lung cancer diagnosis." (PMID 36147748, 2022). "In addition, low EpCAM protein levels were found in highly metastatic human lung cancer cells, including A549, Calu-6, H727, and H460, but high in poorly metastatic lung cancer cells, including H1650, H1975, H3255, and HCC827." (PMID 36077658, 2022). "According to published data, in some cases lung cancer patients EVs had low levels of EpCAM." (PMID 35135541, 2022). "Histone deacetylation, another epigenetic regulation, also caused EpCAM repression, which could be reversed by HDAC inhibitor MS-275 in highly metastatic lung cancer cells Calu-6, H727, H460, and A549." (PMID 36077658, 2022). "Thus, we also performed a functional study of CRISPR/Cas9-mediated lncCDH5-3:3 knockout (KO), and overexpression outcomes on the CDH1 and EPCAM expression, cell cycle, proliferation, and apoptosis in lung cancer cells." (PMID 35159188, 2022). "TGFβ overexpression strongly inhibited the expression of EpCAM in both human and murine lung cancer cells, but stimulated the expression of SNAI2, which could bind to the E-box in epcam promoter to suppress its transcription." (PMID 36077658, 2022). "Lung cancer stem cells typically express EpCAM, CD44, CD90, and CXCR-4." (PMID 35216378, 2022). "PBMCs of 42 healthy volunteers were examined, revealing that the ratio of CD45+EpCAM+ in PBMCs of patients with lung cancer was significantly higher than that of healthy volunteers (patients 0.244 ± 0.353 vs. heath volunteers 0.012 ± 0.004, presented as mean ± SD)." (PMID 36147748, 2022). "In particular, following ZEB1 regulation, the acetylation levels of H3K9, H3K27, and H4 are decreased at the EpCAM promoter, as detected by ChIP experiments, and these reduced histone acetylation have a predominant role in EpCAM inhibition in lung cancer cells." (PMID 35484625, 2022). "Moreover, the proportion of CD45+EpCAM+ cells in PBMCs of patients with lung cancer was found to be significantly higher than that of healthy volunteers." (PMID 36147748, 2022). "Thus, epigenetic regulation is one of the mechanisms controlling EpCAM expression in both primary and metastatic lung cancers and its expression switch from upregulation to downregulation during tumor progression." (PMID 36077658, 2022). "Our results showed CD45+EpCAM+ cells were also present in lung cancer patients' PBMCs." (PMID 36147748, 2022). "Comparing the two, the specificity of CD45+EpCAM+ cell ratio for detecting lung cancer was higher." (PMID 36147748, 2022). "EpCAM is perhaps the best known epithelial cell adhesion molecule for the fact that it is expressed in the majority of human epithelial cancers, including colorectal, breast, gastric, prostate, ovarian, and lung cancer." (PMID 36428760, 2022). "However, both genetic (gene amplification) and epigenetic (promoter hypomethylation) modification contribute to EpCAM upregulation in primary lung cancers." (PMID 36077658, 2022). "It has been reported that high expression of EpCAM was closely related to lung cancer metastasis and poor prognosis, thus might play an important role in the occurrence and development of lung cancer." (PMID 34522164, 2021). "PDL1 expression was identified in EPCAM-positive CTCs isolated from a lung cancer patient." (PMID 32486306, 2020). "The EpCAM was also found to be repressed by G9a in lung cancer." (PMID 32292512, 2020). "Subpopulation of nonsmall cell lung cancer (NSCLC) triple-positive for EPCAM, ALCAM, and CD44 possessed CSC characteristics, including being highly proliferative, having greater clonogenicity, ability for self-renewal through spheroid formation, and chemoresistance." (PMID 32085563, 2020).
lung carcinoma (continued). "In this article, we selected aptamers ECM-APT-01 and ECM-APT-02 against the epithelial cell adhesion molecule (EpCAM) expressed on primary lung cancer cells isolated from tumors of patients with non-small cell lung cancer (NSCLC) using competitive displacement by monoclonal EpCAM antibody." (PMID 30871104, 2019). "We selected DNA aptamers to the epithelial cell adhesion molecule (EpCAM) expressed on primary lung cancer cells isolated from the tumors of patients with non-small cell lung cancer using competitive displacement of aptamers from EpCAM by a corresponding antibody." (PMID 30871104, 2019). "The resulting aptamers clones showed good nanomolar affinity to EpCAM-positive lung cancer cells." (PMID 30871104, 2019). "Furthermore, we showed that rVAR2 resulted in a higher CTC yield in blood samples from prostate, pancreatic, and lung cancer patients as compared to EpCAM-based isolation of patient-matched samples." (PMID 30115931, 2018). "Moreover, this study is the first description of tumor-derived MPs expressing the EpCAM antigen in the pleural liquid from lung carcinoma patients." (PMID 26689993, 2016). "First, EpCAM protein expression was analysed in primary and metastatic lung cancer tissue." (PMID 27302574, 2016). "Conversely, MTA1 knockdown in the three lung cancer cell lines suppressed EpCAM protein expression." (PMID 26698569, 2015). "In addition, a strong positive correlation was observed between MTA1 and EpCAM in IHC data, and MTA1 and EpCAM overexpression predicted poor prognostic in lung cancer cases." (PMID 26698569, 2015). "Furthermore, these lung cancer cells with stably overexpressed or silenced MTA1 were transfected with siEpCAM or EpCAM-expressing plasmids and then subjected to western blot, invasion and migration assays." (PMID 26698569, 2015). "We checked the EpCAM expression by overexpressing or silencing MTA1 in lung cancer cells." (PMID 26698569, 2015). "Furthermore, we demonstrated that EpCAM promoted lung cancer cells invasion and migration, and the impaired tumor cell invasion and migration abilities following MTA1-silenging can be rescued by overexpressing EpCAM." (PMID 26698569, 2015). "We revealed a new molecular mechanism of MTA1-mediated invasion and metastasis in lung cancer through downstream target EpCAM, and interfering with EpCAM function may be a novel therapeutic strategy for treatment of MTA1-overexpressing lung carcinoma." (PMID 26698569, 2015). "Thus, we also evaluated the correlation of EpCAM level with clinicopathological parameters and patients’ prognosis in tumor samples from lung cancer patients." (PMID 26698569, 2015). "Indeed, anti-EpCAM has been recently reported to induce proliferation and modulate gene expression in human lung cancer cells A549." (PMID 26718583, 2015). "Furthermore, recent studies have shown that the cell-surface markers CD133 and EpCAM (CD326) are regarded as cancer stem-cell-related markers for many types of cancers including lung cancer." (PMID 25279705, 2014). "We also analyzed the CD133+EpCAM+ cells in the peripheral blood of patients with lung cancer." (PMID 23959111, 2014). "Moreover, lung cancer cells have been identified in the blood based on their expression of cytokeratin or epithelial cell adhesion molecule (EpCAM/CD326)." (PMID 23959111, 2014). "The EpCAM-dependance could be one of the reasons why significant differences in separation efficiency have been reported if the immunomagnetic isolation of lung cancer CTCs (CellSearch®) was compared to size-based filtration CTC-capture (ISET®)." (PMID 25141982, 2014). "EpCAM is perhaps best known for the fact that it is overexpressed in the majority of human epithelial cancers including colorectal, breast, gastric, prostate, ovarian, and lung cancers." (PMID 22132731, 2011).
lung carcinoma (continued). "Therefore, we used a novel mouse lung carcinoma cell line that was isolated from the lung tumour of a c-raf/c-myc double-transgenic mouse as a model to investigate EpCAM signalling." (PMID 19002182, 2008). "We then fractionated exosomes from lung cancer patients and healthy controls into four groups: exosome‐all (total exosomes), exosome‐ΔEpCAM (depleted with anti‐EpCAM), exosome‐ΔEpCAM+Spike (reconstituted with captured EpCAM+ exosomes), and exosome‐IgG (isotype antibody control)." (PMID 41159542, 2026). "In addition, IL-4Rα blockade in the presence of IFNγ + TNFα significantly enhanced the autologous T-cell mediated cancer cell killing as measured by Annexin V positivity of EpCAM-expressing lung cancer cells and promoted the cancer cell elimination induced by PD-1 blockade." (PMID 40091029, 2025). "Importantly, we have found minimal overlap between CD45 and EpCAM staining in lung cancer samples." (PMID 40525275, 2025). "In addition, EpCAM is strongly upregulated in primary lung cancer but downregulated in metastatic lung cancer, which can be attributed to the shift of EPCAM promoter hypomethylation in primary lung cancer to EPCAM promoter hypermethylation in metastatic lung cancer." (PMID 38791091, 2024). "In addition, exosomal membrane surface proteins such as EGFR, placental alkaline phosphatase, epithelial cell adhesion molecule (EpCAM), and Alix are significant predictors of long-term overall survival in lung cancer patients and can be used as potential prognostic markers." (PMID 37122754, 2023). "Therefore, the detection of CD45+EpCAM+ cells in PBMCs may be helpful for the early screening and auxiliary diagnosis of lung cancer." (PMID 36147748, 2022). "Interestingly, we could show both in lung cancer as well as in this study that survival after brain metastasis diagnosis correlates with CTC detection when using EpCAM-dependent enrichment." (PMID 31481116, 2019). "Therefore, we hope that the results presented here may be helpful in the development of anti-metastatic strategies to potentially target the MTA1 alone or combined with EpCAM to inhibit the metastasis of lung cancer." (PMID 26698569, 2015). "Thus, this study was aimed to explore whether MTA1 was able to upregulate EpCAM expression and, consequently, modulate its effects on invasion and migration of the lung cancer cells as well as patients’ prognosis." (PMID 26698569, 2015). "The results indicated that EpCAM based capturing may miss large fraction of CTCs in lung cancer." (PMID 24324600, 2013). "In other works, researchers focus on the evaluation of EpCAM+ CD45+ cells both in tumor tissues and in the peripheral blood of patients with lung cancer." (PMID 39941799, 2025). "EPCAM is a transmembrane glycoprotein mainly expressed in epithelia and epithelial-derived tumors, including CRC, lung carcinoma, and other epithelial tumors." (PMID 41551611, 2025). "Flow cytometry evaluated specific EpCAM-Apt binding to EpCAM expressing SK-MES-1 and A549 small lung cancer cells." (PMID 37149607, 2023). "The EMT status induced by TGFβ strongly impeded EpCAM expression in A549, HCC827, and H358 lung cancer cells." (PMID 36077658, 2022). "ROC curve analysis indicated that the sensitivity and specificity of serum CEA for detecting lung cancer were 86.84% and 50.00%, while the sensitivity and specificity of the CD45+EpCAM+ cell ratio were 81.58% and 88.89%, respectively." (PMID 36147748, 2022). "In lung cancer, CD45+ cells are mostly harboring lymphocyte markers CD3 and CD19, and the proportion of CD3+EpCAM+ cells is higher than that of CD19+EpCAM+ and CD16+EpCAM+ cells." (PMID 36147748, 2022). "We performed a correlation analysis between NCAPG2 and 13 lung cancer stemness markers using the TCGA database and found that NCAPG2 was highly correlated with ABCC1, MYC, and EPCAM." (PMID 36139554, 2022).